IL10 (interleukin 10)
Diseases named in the same sentence as IL10 in open-access papers (continued):
Sharing a sentence is not in itself a finding about the gene and the disease.
infection (continued). "We previously reported that early type I IFN signaling (days 0 to 4 p.i.)promoted the development of IL-10+IFN-γ+ T regulatory 1 (Tr1) populations that during the second week of infection functioned to constrain anti-Plasmodium humoral immunity." (PMID 33529242, 2021). "Upregulation of PD-L1 by macrophages and of PD-1 by CD4+, CD8+ T and Tregs IL-10+Foxp3+ upon infection was also observed." (PMID 33776999, 2021). "Taken together, these data showed that IL-10 overexpression during the early stages of the M. tuberculosis infection promoted progression of infection and resulted in the hosts’ rapid death." (PMID 34554927, 2021). "The severity of infection was described based on cytokines IL-6, IL-8, and IL-10 in cellular microparticles (cMPs)." (PMID 34305892, 2021). "p75(NTR) was upregulated upon infection and affected innate immune cell behavior to producing the cytokines: IL-10, IL-6, and IL-1α." (PMID 34124260, 2021). "IL-10 expression levels were also significantly upregulated, indicating that the anti-inflammatory response was induced by infection with the toxigenic strain." (PMID 33665221, 2021). "Overall, the mRNA levels of inflammatory cytokines (TNFα, IL-6, and IL-10) were slightly elevated compared with what is seen in the lungs of deer mice (~2–5-fold increase) following experimental infection with SNV39." (PMID 34127676, 2021). "To do this, we infected mice and induced IL-10 overexpression starting at day 5 after infection (as above) and analyzed the kinetics of the CD4+ T cell response in the lungs." (PMID 34554927, 2021). "Further using intracellular cytokine assay, we observed a three-fold increase in the number of IL-10 secreting splenic Transitional T3 B cells while infection with both antimony drug- sensitive and -resistant strain." (PMID 34209841, 2021). "Although variable levels of IL-10 have been reported in individuals infected by ZIKV along the acute phase of the infection, in our series IL-10 levels were elevated in both groups of patients in the acute phase of the infection." (PMID 33776990, 2021). "IL-10 is a critical anti-inflammatory cytokine secreted by monocytes following their infection with pathogens, and increased production of IL-10 following infection by other poxviruses has been previously reported." (PMID 34211465, 2021). "For that reason, macrophages produce IL-10, a potent anti-inflammatory cytokine produced by macrophages as a negative-feedback mechanism to dampen excessive inflammation during infection." (PMID 34122722, 2021). "IL-4, IL-6, IL-10, and TGF-β were associated with infection progression, while IFN-γ was correlated to tissue damage." (PMID 34276650, 2021). "The results showed that the ability of MS_Rv2650c to stimulate the secretion of cytokines TNF-α, IL-1β, IL-6, and IL-10 was lower than that of MS_Vec after 24 h of infection (paired t-test; P = 0.000006, P = 0.004, P = 0.01, P = 0.00002, respectively)." (PMID 35111145, 2021). "MoDCs presented a reduced production of IL-12 and TNF-α after 24 h of infection with the Tehuantepec strain, while BM-DCs showed diminished IL-12 secretion but higher IL-10 production 24 h post-infection." (PMID 33897690, 2021). "Among other functions, IL-10 is also stimulatory toward TCD8+ cells, and this can be associated with the decrease in the CFU at 60 days post-infection in CD18low mice." (PMID 33796477, 2021). "Here, we consider the known multi-faceted immune regulatory role of IL-10, both in protecting the lung from injury and in defense against infections, as well as its potential cellular source." (PMID 33746948, 2021). "During infection, it is produced to limit inflammation and collateral tissue damage, such as during T. gondii infection, IL-10 produced by Th1 cells is essential to limit an otherwise excessive and detrimental Th1 cell response." (PMID 33748214, 2021). "IL-10 is produced transiently by CD8 T cells in the brain of coronavirus-infected mice at the peak of infection." (PMID 34393976, 2021).
infection (continued). "Changes in the expression of cytokines IL-10, IL-4, IL-6, IL-1β and TNF-α were measured in BALB/c mice, the susceptible host of S. japonicum, and in M. fortis, the resistant host, before infection and on 3, 7, 10 and 14 dpi, respectively." (PMID 34689797, 2021). "We used the recently described pMT-10 transgenic mouse line wherein IL-10 overexpression can be induced at different stages of infection by feeding the mice a 2% sucrose solution with 50 mM zinc sulfate." (PMID 34554927, 2021). "Here, we suspect that the increase in IL-10 constitutes a particular COVID-19 disease endotype that contributes to lung protection but also interferes with viral clearance very early following infection up to critical illness." (PMID 33746948, 2021). "Having defined a feed-forward signaling loop between il-10 and butyrate following infection with H. diminuta, this study identifies the gut microbiome as a critical component of the anti-colitic effect of this helminth therapy." (PMID 34517928, 2021). "Using a mouse model of infection, our data shows that neutrophils contribute significantly to IL-10 production during the acute phase of S. pneumoniae infection in the lungs, displaying a regulatory role and influencing disease outcome." (PMID 33995357, 2021). "In vivo, we identified the recruitment of two neutrophil subpopulations in the lungs following infection, which exhibited clear morphological differences and a distinctive profile of IL-10 production at 48 h post-infection." (PMID 33995357, 2021). "Elevated concentrations of MIP-1α, TNFα, IL-12, and IL-10 hindered clearance of incident infections emphasizing the role played by local immune mediators in the long-drawn battle against the elimination of the virus." (PMID 33996630, 2021). "IL-10 levels in the infected control group peaked on the 7th day after infection, and then decreased slightly, but continued to increase after 14 days of infection." (PMID 33717108, 2021). "Although IL-10 deficiency leads to a rapid acceleration and augmentation of monocyte activation, this is transient and by d56 post infection, monocyte activation in B6.Il10-/- mice has returned to a homeostatic baseline." (PMID 34557190, 2021). "Surprisingly, significant reduction in the level of antibodies was observed in the protected mice, and levels of cytokines including IFNγ, IL-2, IL-8, IL-10, and IL-12, and of nitric oxide after infection with B. rodhaini also diminished." (PMID 34414129, 2021). "The proportions of IFN-γ and IL-10 secreting γδT cells were decreased after P. yoelii NSM infection (P < 0.05)." (PMID 35127555, 2021). "The present study suggests that early in infection, when bacterial burdens are higher and inflammation is increasing, IL-10 production is stimulated." (PMID 34026898, 2021). "Expression of the anti-inflammatory cytokine IL-10 was significantly higher in LCMV-infected M-CSF cells compared to mock infection and further stimulation with R848 significantly enhanced the production of IL-10 in LCMV-infected M-CSF cells." (PMID 33331816, 2021). "On the other hand, the resistant group displayed a decrease in the involvement of both IFNγ and IL-10 in the network after infection diagnosis." (PMID 33617528, 2021). "Burned mice infected with P. aeruginosa M2 showed increased circulating proinflammatory cytokines (IL-6, IL-1β, TNF-α, and IFN-γ) and a rise in anti-inflammatory IL-10 late during infection once clinical symptoms were observed." (PMID 34152806, 2021). "These regulation of parasite antigen-specific IL-19 and IL-24 expressing CD8+ T cells are more dependent on the stage of the infection than on IL-10, IL-1β, and IL-23 as observed in the regulation of CD4+ T cell response." (PMID 34603287, 2021). "IL-10 is a cytokine with anti-inflammatory properties that plays a central role in infection by limiting the immune response to pathogens and preventing the host from overactive inflammatory responses." (PMID 35058927, 2021).
infection (continued). "On the 2nd day post-infection, E. coli challenge, particularly with E. coli O78, displayed significantly upregulated levels of ileal IL-6 and IL-8, but ileal IL-10 level tended to be downregulated in comparison to the control group." (PMID 34903932, 2021). "In contrast, the resistant strain SV/129 mice upregulate IL-10 expression after infection in CD4+ T cells only 8 weeks post-infection." (PMID 33680991, 2021). "Consistent with this idea, blocking IFNα or IL-10 during Clone-13 infection rescues the Th1 effector compartment and improves viral control, although this likely depends on the rate of viral replication." (PMID 33684030, 2021). "IL-10 is an immune regulatory factor important for the homeostatic control of infection and inflammation." (PMID 35082787, 2021). "In vitro infection of Siglec-10 overexpressing cells with pseudaminic acid residues containing flagella resulted in increased IL-10 expression in a p38-dependent manner." (PMID 33708213, 2021). "To determine the cytokine’s chronic-phase impact, in another group we induced IL-10 overexpression starting at day 30 after infection." (PMID 34554927, 2021). "We reviewed clinical observations in SARS-CoV-2 and SARS-CoV infected patients and the roles of the anti-inflammatory cytokine IL-10 in experimental animal models of lung injury and infection as well as in human pulmonary pathology and infection." (PMID 33746948, 2021). "The mRNA expression levels of IFN-γ, and the interleukins (ILs) IL-10 and IL-6 were also significantly upregulated in the infected animals at day 5 post-infection." (PMID 34370799, 2021). "Induction of IL-10 by M. tuberculosis Eis protein also increases autophagy potential in macrophages during infection." (PMID 34346699, 2021). "The differentiation of suppressive myeloid cells in this cell model depended on the cytokines IL-6 and IL-10, indicating a role for systemic factors in inducing myeloid dysregulation in patients with severe infections." (PMID 34103408, 2021). "For P. vivax infection, in spite of the high plasma levels of IL10 and TGFβ during the infection phase, minimum parasite density over the threshold level is required for pathogenesis induction." (PMID 34698295, 2021). "FICZ enhanced the expression of il-17, il-22, il-10, and tgf-b mRNAs at both periods but reduced il-6 levels at 96 hours of infection." (PMID 33936043, 2021). "IFN‐g, TNF‐a, IL‐6, and IL‐10 were all increased after challenge, but IL‐6 and IL‐10 levels dropped quickly 3 days post‐infection." (PMID 34176237, 2021). "Interleukin-10, as an anti-inflammatory cytokine, has a protective property in inflammation and infection by limiting the immune response to pathogens." (PMID 34237550, 2021). "Our findings demonstrated that the infection by T. gondii induced the IL-4, IL-10 and TGF-β1 production, however, COX-2 inhibitors decreased these cytokines and also contributed to parasitism control." (PMID 34135407, 2021). "We evaluated the production of TNF-α, IL-6 and IL-10 at different times from viral adsorption to 6 h and 24 h post infection." (PMID 32316163, 2020). "From the analysis, anti-HCV positive participants who had recovered from the infection had significantly higher [67.2 (50.6–113.1) pg/ml] concentration of IL-10 compared to those with active infection (48.5 (30.3–63.2) pg/ml) p = 0.012." (PMID 33028385, 2020). "T cells are the predominant producers of IL-10 later in M. tuberculosis infection, at ~21 days post-infection, where they contribute to impaired clearance." (PMID 32425944, 2020). "Nevertheless, while the expression of IL-23 remained highly increased in infected cells during the infection, expression of IL-10 culminated at 2 h pi and then it gradually dropped." (PMID 32070192, 2020). "The level of IL-10 mRNA in the lungs of klotho WT mice significantly increased at 1 day post-infection and decreased at 3 days post-infection." (PMID 33329595, 2020).
infection (continued). "The production of IL-10 in the supernatant of L. amazonensis–infected RAW264.7 cells was observed after 72 h of infection and the use of an antibody to abrogate it, preventing L. amazonensis proliferation." (PMID 32596164, 2020). "The mRNA expression of the pro-inflammatory cytokines IL-1β, IL-8, and TNF-α, as well as the anti-inflammatory cytokine IL-10 were quantified by qRT-PCR after infection of THP-1 macrophages with the various mycobacteria for 18 h." (PMID 32117140, 2020). "Higher production of IL-17A, IFN-γ, IL-10, IP-10, GM-CSF, sFasL, Granzyme A, Granzyme B, Granulysin, and Perforin following infection positively correlated with HIV replication." (PMID 33214610, 2020). "In contrast, infection with MCMV down-regulated the expression of IL-10 and increased production of inflammatory cytokines IL-6 and TNFα." (PMID 32455939, 2020). "BMMs infected with both Δhly and ΔhlyΔfla L. monocytogenes secreted significantly more IL-10 than uninfected BMMs four hours post-infection." (PMID 32634175, 2020). "In this study, we did such work and found that infection with C. psittaci will increase the replication of H9N2, decrease the iNOS–NO pathway, and raise the IL-6 and IL-10 expression of HD11 cells by H9N2 infection." (PMID 32326284, 2020). "In this study, we investigated how C. jejuni transmitted from birds raised in different husbandry influenced its virulence in subsequent infection using Il10−/− mice." (PMID 33257743, 2020). "Ablating IL-10 with ΔT vaccination increases survival and protection against virulent Coccidioides infection and increases recall protection post infection." (PMID 33262956, 2020). "The level of IL-10 mRNA in the lungs of klotho KO mice increased at 1 day post-infection and subsequently decreased significantly." (PMID 33329595, 2020). "ALVAC immunization within the first 24 hours of infection increases the production of the pro-inflammatory cytokines IL-1, IL-6, and IL-10 by 20–50-fold." (PMID 32163525, 2020). "In this work, we investigated the bacterial and host factors that contribute to secretion of IL-10 and immunosuppression following infection with a strain of L. monocytogenes that cannot escape from host cell vacuoles." (PMID 32634175, 2020). "IL-10 is an anti-inflammatory cytokine that suppresses Th1 cells, NK cells, and macrophages during infection." (PMID 32309522, 2020). "Serum IL-10 levels at day 7 were significantly higher in SAH patients who developed any kind of infection, CVS or shunt-dependent hydrocephalus." (PMID 32106601, 2020). "L. major lysate-stimulated lymphocytes from EBI3−/− mice secrete fewer IFN-γ and high IL-4, IL-10, and IL-13 as compared to the lymphocytes from the control mice on the second and third week post-infection." (PMID 32849534, 2020). "Further, Cse−/− mice had lower levels of anti-inflammatory cytokines IL-10 and IL-13 at 2 weeks post-infection, which was followed by a significant increase in IL-10 levels after 3 weeks of infection." (PMID 33330130, 2020). "M2 cell surface marker CD206 and IL-10 cytokine, on the other end, showed their highest expression levels (p < 0.05) in cells pre-exposed to nicotine prior to infection (respectively)." (PMID 32370298, 2020). "IL-10 itself is a key regulator of immune responses during infections, where it plays a two-sided role by both promoting pathogen persistence as well as limiting excessive Th1 and CD8+ T cell responses that cause immune pathology." (PMID 32152316, 2020). "HCMV uses the viral IL-10 proteins to manipulate the immune system during lytic and latent phases of infection." (PMID 32582563, 2020). "IL-10 producing B cells (B10 cells) play an important immunoregulatory role in various autoimmune and infection conditions." (PMID 32849556, 2020).
infection (continued). "On the contrary, nicotine in CD active smokers associated with bacterial infection induce M1-macrophage polarization, upregulation of iNOS, IL-6, and TNF-α, downregulation in CD206, IL-10, decrease in caspase-3 activity, and increase in infection burden." (PMID 32370298, 2020). "The population of IELs accompanied with the secretion of cytokines, such as IFN-γ and IL-10, rapidly increases in early infection by E. cuniculi." (PMID 32670257, 2020). "The results strongly suggest that cortisol, via intracrine interaction with GRs, is important for IL-10-dependent control of the activity of macrophages and for the regulation of M1/M2 polarization to finally determine the outcome of an infection." (PMID 33255713, 2020). "Serum IL-10 levels were significantly higher on day 7 in patients who developed any kind of infection, cerebral vasospasm (CVS) or chronic hydrocephalus." (PMID 32106601, 2020). "None of these papers investigated the potential balance between the pro-inflammatory and anti-inflammatory effects of IFN-γ and IL-10, respectively, on the outcome of this infection, which would anyhow have been technically challenging." (PMID 33101315, 2020). "Previous reports suggest that adenosine produced by ectonucleotidase, during activation of the ATP pathway, during infection contributes to the production of IL-10 and IL-6." (PMID 32555598, 2020). "In the short-term experiment, after infection with the parasite and stimulation with F/T of the parasite, the IL-10 level in G1 (immunized with L. lactis-PpSP15-EGFPcwa) was decreased by 2.3x (~43%)." (PMID 31899767, 2020). "CSV-treated RAW 264.7 cells significantly induced production of IFN-γ and IL-12 while decreased IL-10 production at the late stage of infection compared to PBS-treated control cells." (PMID 33553273, 2020). "As concerning this mechanism, it was reported for B. bovis that in young calves the infection with virulent strains of the pathogen is followed by an early production of IL-12 and IFN-γ, occurring before the influence of IL-10 and associated to protection." (PMID 32751625, 2020). "Human cytomegalovirus (HCMV) exploits the interleukin-10 (IL-10) pathway as a part of its infection cycle through the manipulation of the host IL-10 signaling cascade." (PMID 33013921, 2020). "Of the two mutants that induced reduced IL-10 secretion, we focused on understanding the contribution of lgt to the induction of IL-10 secretion from BMMs because the other mutant, which had a transposon insertion in lmo0709, had reduced infection capability." (PMID 32634175, 2020). "Intranasal administration of recombinant IL-10 or macrophages from wild-type mice rescued IL-10-/- mice from lethal infection by promoting the antibacterial function of macrophages." (PMID 33042864, 2020). "IL-10 is secreted during the early phases of infections by cells of the innate immune response (NK, Mast cells, APC, and granulocytes) and nonimmune cells types (fibroblasts, keratinocytes) in order to regulate local immune mediated damage." (PMID 33066100, 2020). "Second, there was a significant increasing trend in the Th1/ Th2 cytokines IL-2, TNF-a, IL-4, and IL-10 on 5–7 dpi during the middle stage of infection." (PMID 33180882, 2020). "IL-10 secretion four hours post-infection of BMMs with deletion mutants and transposon mutants identified in genetic screen." (PMID 32634175, 2020). "alternatively activate macrophages and Ly6C- patrolling monocytes) can constitute a source of IL-10 required to dampen some specific aspects of immunopathology (e. g. liver injury) during the early stages of infection." (PMID 32012211, 2020). "The role of IL-10 secretion in patients with UC in determining the clinicopathological outcome of infection merits further study." (PMID 32695157, 2020). "It has been demonstrated that IL-10 has a significant role in infection progression, so maintaining low levels of IL-10 implies an improvement in the protective immune response." (PMID 32667458, 2020).